MSTN (myostatin)
Diseases named in the same sentence as MSTN in open-access papers (continued):
Sharing a sentence is not in itself a finding about the gene and the disease.
sarcopenia (continued). "Nevertheless, the relationships of Myostatin and Decorin with sarcopenia are not clear, as some studies found association between these myokines and sarcopenia, whereas in others the association is unclear or is present in males but not in females." (PMID 36499366, 2022). "In the present study, we tried to determine if coenzyme Q10 and the skeletal muscle protein biomarkers such as albumin, creatine kinase, irisin, and myostatin, could be used to assist in the diagnosis of sarcopenia." (PMID 35453410, 2022). "Treatment targeting myostatin inhibition may have promising results for patients with sarcopenia or low gait speeds." (PMID 35010726, 2022). "Studies emphasized that myostatin and TNFα are potential candidates for sarcopenia obesity." (PMID 35250869, 2022). "This study aims to investigate the correlation of insulin-like growth factor-1 (IGF-1) levels as an anabolic factor, myostatin levels, and insulin resistance as catabolic factors with sarcopenia in the pathogenesis of sarcopenia in elderly patients undergoing hemodialysis." (PMID 35371569, 2022). "In a previous report, the myostatin/SMI ratio in older Korean women was negatively associated with HGS but the myostatin/SMI ratio was not presented as an indicator of sarcopenia in CKD in this study." (PMID 36287929, 2022). "Although these purported mechanisms of myotube atrophy in ESLD require further exploration, interventions targeting myostatin and proteolytic pathway regulators may provide a promising approach to offset sarcopenia progression in chronic liver disease." (PMID 35406665, 2022). "Myostatin is a key mediator in catabolism within muscle cells and has a significant role in sarcopenia; inhibition of its related signaling pathway can be a therapeutic strategy for management of sarcopenia and possibly its consequences." (PMID 35010726, 2022). "Our study suggests that IS levels are more appropriate than myostatin levels to predict sarcopenia." (PMID 36287929, 2022). "Additional investigations are needed to confirm whether myostatin is a biomarker for sarcopenia in advanced cases of CKD/HD." (PMID 34063269, 2021). "Various negative regulators increase protein degradation in muscular dystrophy and sarcopenia, and, of these, myostatin (MSTN) effectively inhibits muscle growth, and thus is regarded as a potential curative target for the treatment of muscle wasting associated diseases." (PMID 33467209, 2021). "Although myostatin might be involved in development of sarcopenia in CKD/HD, limited data are available." (PMID 34063269, 2021). "We could speculate that passive stretching is a potential intervention to counter, at least in part, sarcopenia via myostatin inhibition." (PMID 34315961, 2021). "Therefore, the key contribution to sarcopenia in patients with chronic liver disease is the hyperammonemia-induced upregulation of myostatin." (PMID 33803020, 2021). "The pathophysiology of sarcopenia is complex and is attributable to reduction in caloric consumption, denervation of muscle fibres, intracellular oxidative stress, hormonal decrease, and enhanced myostatin signalling." (PMID 33165641, 2021). "Accordingly, myostatin has been proposed as a biomarker for sarcopenia." (PMID 34299795, 2021). "Moreover, blockade of sarcopenic markers, such as myostatin, not only prevents sarcopenia but also increases insulin sensitivity in old mice." (PMID 34067004, 2021). "The importance of MSTN has been reported in several disease conditions, including cachexia, sarcopenia, muscular atrophy, and other muscular dystrophies such as Duchenne muscular dystrophy, and its inhibition is an important strategy for managing these disease conditions." (PMID 34500839, 2021). "Despite these challenges, myostatin remains an important biomarker for dogs, both as a therapeutic target and potentially in further characterizing muscle atrophy and muscle wasting secondary to sarcopenia and cachexia in dogs." (PMID 34368273, 2021).
sarcopenia (continued). "Myostatin has been proposed as a main mediator for sarcopenia, especially in CKD." (PMID 34299795, 2021). "Another important factor in the development of sarcopenia is an imbalanced ratio of myostatin and follistatin, which may stem from inflammation as well as genetic factors." (PMID 34680417, 2021). "Myostatin is increased in sarcopenia and plays a role in diabetic muscle atrophy." (PMID 34199375, 2021). "Thus, further research is necessary to develop the most effective methods of blocking myostatin in order to safely increase the muscle mass and strength in patients with sarcopenia." (PMID 34680417, 2021). "It is still unknown whether fatty liver promotes sarcopenia by activation of myostatin production in skeletal muscles or whether sarcopenia promotes liver disease by myostatin-related activation of hepatic stellate cells." (PMID 33204675, 2020). "Despite the fact that such inconsistencies in results might be discouraging for considering serum myostatin as a valid biomarker of sarcopenia, we believe that it is important to research into possible causes of such differences between studies." (PMID 32796600, 2020). "It has been well-known that cirrhotic patients with sarcopenia had poorer survival as compared to those without it, and expression of serum myostatin is associated with sarcopenia." (PMID 33198216, 2020). "However, a thorough understanding of the interrelationship of these markers, as well as establishing a valid measurement methodology for myostatin and revising current research data in the light of new criteria of sarcopenia, is needed." (PMID 32796600, 2020). "Furthermore, myostatin’s ability to predict sarcopenia has to be revised using the latest EWGSOP2 criteria." (PMID 32796600, 2020). "Thus, we propose that knockout of myostatin using the rAAV9–SaCas9 system has significant therapeutic potential in sarcopenia." (PMID 32398787, 2020). "Realistically, drug candidates in the myostatin signalling cascade, well-studied in the context of muscle growth, sarcopenia and cachexia, could rapidly be advanced into clinical trials assessing their therapeutic potential to moderate insulin resistance." (PMID 28469281, 2017). "Clinical trials of myostatin blockade against muscular dystrophy and sarcopenia are now ongoing." (PMID 27992376, 2017). "Therapeutics that inhibit myostatin/activin A signaling are currently undergoing clinical trials for a wide range of indications which include sarcopenia, cancer cachexia, muscular dystrophy, sporadic inclusion body myositis and rehabilitation post-orthopedic surgery (for reviews, see34,54)." (PMID 29079832, 2017). "Augmentation of the myogenic and antioxidant responses through treatments such as anti-myostatin therapies and/or anti-oxidants may prove effective to prevent/slow progressive sarcopenia in CKD." (PMID 27486747, 2016). "Our data suggest that myostatin may contribute to the higher prevalence of sarcopenia in women but acts as a homeostatic regulator of muscle mass in men." (PMID 26180626, 2015). "Considering that the plasma MSTN level was a potential biomarker for sarcopenia and PEW, measurement of plasma MSTN may be clinically beneficial for CKD patients." (PMID 26502079, 2015). "In addition, myostatin signaling inhibition for mice and calorie restriction for mice and rhesus monkey have been shown to counteract sarcopenia." (PMID 25221510, 2014). "Further studies are needed to conclusively address the role of myostatin in sarcopenia." (PMID 24092876, 2013). "It’s product MSTN was suggested to contribute to sarcopenia after it was shown that MSTN deficient mice did not experience the same age-related muscle atrophy as wild-type controls." (PMID 22934016, 2012). "In addition, many researchers have focused on inhibiting myostatin for treating various muscle disorders such as muscular dystrophy, cachexia, and sarcopenia." (PMID 22500226, 2012).
sarcopenia (continued). "Additionally, manipulating myostatin levels may prove beneficial in treating sarcopenia in older individuals." (PMID 40427596, 2025). "Additionally, in animal studies, GLP-1RA may have protective effects on skeletal muscle against sarcopenia by increasing insulin sensitivity, inhibiting myostatin expression, and increasing mitochondrial biogenesis." (PMID 40226371, 2025). "We also found that serum myostatin level was significantly higher in patients with Child-Pugh B or C cirrhosis than in those with Child-Pugh A cirrhosis, indicating that the synthesis of muscle protein is more suppressed, or more likely to develop sarcopenia, as liver function worsens." (PMID 39940810, 2025). "In addition, monitoring of myostatin could also be beneficial in evaluating the presence of sarcopenia." (PMID 39126043, 2024). "Apart from well-established factors such as uremic toxins accumulation, protein loss during dialysis, metabolic acidosis, multiple comorbidities, myostatin and angiotensin II overexpression, hyperparathyroidism may also play a pivotal role in the pathogenesis of uremic sarcopenia." (PMID 39478830, 2024). "Furthermore, some interventions might protect from sarcopenia by directly or indirectly reducing the expression or activity of myostatin." (PMID 38791164, 2024). "Additionally, we found significantly lower MSTN levels in patients with sarcopenia." (PMID 38542721, 2024). "Body composition and muscle strength are at least in part genetically determined, consequently polymorphisms in pathways important in muscle biology (e.g., the activin/myostatin signalling pathway) are hypothesised to contribute to the development of sarcopenia." (PMID 37963137, 2023). "Obesity and NAFLD, as closely related conditions, share many potential mechanisms that could worsen sarcopenia, including increased inflammation, hormonal derangements, altered myokines secreted by skeletal muscle (myostatin, adiponectin), physical inactivity, and insulin resistance." (PMID 38137592, 2023). "Myostatin antibody and testosterone may have a beneficial effect on treating sarcopenia." (PMID 36938648, 2023). "Therefore, the Akt/mTOR and FOXO1/myostatin signaling pathways may be the key to protein synthesis improvement in sarcopenia." (PMID 35250869, 2022). "Furthermore, myostatin levels also positively correlated with sarcopenia status." (PMID 35371569, 2022). "Thus, CP and CTP supplements may represent an effective therapeutic approach for age-associated sarcopenia by increasing IGF-1 and decreasing myostatin expression." (PMID 35566067, 2022). "Indeed, opposite findings or a lack of association between circulating myostatin and frailty/sarcopenia conditions have been reported." (PMID 36556504, 2022). "Therefore, myostatin and IS may function as important uremic toxins related to sarcopenia in patients with CKD." (PMID 36287929, 2022). "In older men with sarcopenia (n = 30) randomized to endurance training followed by RT or RT followed by endurance training, serum myostatin levels reduced by 308 pg/mL and 294 pg/mL, respectively, while those randomized to control group maintained their myostatin levels." (PMID 36422286, 2022). "Furthermore, there is a hypothesis that serum myostatin level can be used as a monitoring biomarker for frailty and sarcopenia diagnosis." (PMID 36362238, 2022). "Therefore, there is an urgent need to develop potential treatment options, including an ammonia-lowering approach that blocks the myostatin–activin receptor pathway, as well as hormonal therapy, regenerative therapeutics, and their combinations, to prevent and reverse sarcopenia." (PMID 33803020, 2021). "Since the anabolic influence of testosterone is well known and important in skeletal muscles, testosterone might reverse sarcopenia via multiple signaling pathways, including the suppression of myostatin and muscle cell apoptosis and the stimulation of proliferation pathways in muscle remodeling." (PMID 33803020, 2021).
sarcopenia (continued). "Therefore, a modification of the myostatin metabolic pathway may constitute a contemporary way to inhibit the development of sarcopenia, or reverse the effects of the disease." (PMID 34680417, 2021). "Furthermore, the circulating myostatin is high in patients with both cirrhosis and sarcopenia." (PMID 33898958, 2021). "This can then affect the development of sarcopenia, which is aggravated by the increased skeletal muscle fatty infiltration, reduced protein intake, impaired muscle energetics, the increased expression of myostatin, altered skeletal muscle substrate metabolism, and increased expression of myostatin." (PMID 32934604, 2020). "Since myostatin is related to the down-regulation of skeletal muscle growth, its inhibition may be a strategy for the treatment of muscle disorders, such as disuse muscle atrophy, sarcopenia, muscular dystrophy, cachexia, and cancer." (PMID 32443765, 2020). "Myostatin, is a member of the transforming growth factor beta (TGF-β) superfamily [also known as growth-differentiation factor (GDF)-8], negatively regulates SKM hypertrophy and hyperplasia and it may cause SKM mass loss during aging (sarcopenia) and with metabolic and inflammatory conditions." (PMID 30792697, 2019). "With the aging of our population and sarcopenia becoming of increasing interest, one might speculate that investigative drugs such as the myostatin inhibitors or flavonoids may hold promise for improving muscle strength in postural related progressive kyphosis." (PMID 28369088, 2017). "Serum myostatin might be a serum marker for therapeutic outcome monitoring of sarcopenia." (PMID 26785759, 2016). "However, the role of myostatin in driving sarcopenia is debated." (PMID 25221510, 2014). "Moreover, myostatin-null mice have increased muscle mass and might be protected from sarcopenia, although they demonstrate compromised force production in comparison with controls." (PMID 24092876, 2013). "In addition to changes in androgen and estrogen levels, another important player in the development of sarcopenia in elderly population might be myostatin, a secreted TGFβ family member that inhibits muscle differentiation and growth (as detailed above)." (PMID 22934054, 2012). "In clinical practice, we further revealed the relationship between GHRL, MSTN, CRP, and Hs -CRP through correlation analysis, aiming to further elucidate the potential pathophysiological mechanisms between malnutrition/sarcopenia and inflammation." (PMID 40813643, 2025). "Sarcopenia, a serious consequence of chronic kidney disease (CKD), is driven by elevated myostatin (MSTN), a key inhibitor of muscle growth." (PMID 40243849, 2025). "Our findings revealed that EVs‐derived myostatin, P3NP and TNF‐α were strongly correlated with sarcopenia‐related factors, specifically muscle function and muscle performance, highlighting the potential of circulating EVs as reliable biomarkers for sarcopenia." (PMID 40162588, 2025). "Apart from the previously noted findings, there was a marked reduction in Collagen-I levels in skeletal muscle after MSTN-ASO treatment, suggesting an alleviation of muscle fibrosis—a secondary but critical aspect of CKD-induced sarcopenia." (PMID 40243849, 2025). "Current evidence remains predominantly preclinical, with limited studies examining circulating myostatin/irisin profiles in RA patients with OPF and sarcopenia comorbidity." (PMID 40593203, 2025). "Several studies investigated MSTN inhibition’s ability to promote muscular strength and functionality in CKD, exploring its benefits as a therapeutic target for preventing sarcopenia." (PMID 40243849, 2025). "To further evaluate the role of iron in sarcopenia, we examined the effect of deferiprone on TGF superfamily member myostatin, a factor that promotes catabolism and leads to skeletal muscle atrophy." (PMID 39797505, 2025).
sarcopenia (continued). "The study found lower levels of MSTN and Act A in the IBD patients, and a further decrease in the concentrations of the two proteins in those with sarcopenia." (PMID 38542721, 2024). "The aim of this study is to assess the usefulness of determining levels of myostatin (MSTN) and activin A (Act A) as potential markers of disease activity and occurrence of sarcopenia in Crohn’s disease and ulcerative colitis patients." (PMID 38542721, 2024). "The highlighted sarcopenia biomarkers in this study included the low expression of IGF-I and TNF-α, high serum MSTN, and low serum vitamin D levels; however, the current literature is limited, and further research is required." (PMID 39769198, 2024). "However, whether PTH interplays in the established pathogenesis of sarcopenia and myocyte changes, such as oxidative stress, inflammation, mitochondrial and satellite cell dysfunction, and myostatin overexpression, remains unexplored and should be addressed in further research." (PMID 39478830, 2024). "The highlighted sarcopenia biomarkers included the low expression of insulin-like growth factor (IGF-I) and tumor necrosis factor-α (TNF-α), along with high serum myostatin and low serum vitamin D levels." (PMID 39769198, 2024). "There are also reports on the involvement of myostatin (MSTN) and activin in nutritional status disorders, including sarcopenia." (PMID 38542721, 2024). "Thus, ItP of myostatin inhibitory peptide may be a useful strategy for treating sarcopenia." (PMID 36986496, 2023). "Therefore, increased myostatin levels may be related to sarcopenia." (PMID 36287929, 2022). "In conclusion, our results demonstrated that IGF-1, myostatin, and HOMA-IR levels correlated with sarcopenia status in elderly patients undergoing HD." (PMID 35371569, 2022). "On the contrary, myostatin and HOMA-IR levels were positively correlated with sarcopenia status in elderly patients undergoing hemodialysis (all p < 0.05)." (PMID 35371569, 2022). "The factors of sarcopenia in ESKD are complex, including insulin resistance, inflammation, malnutrition, abnormal myogenic regulatory factors, increased myostatin, and decreased physical activity." (PMID 36191303, 2022). "Clinical studies reported aerobic exercise in people with sarcopenia increases IGF-1 and decrease muscle RING-finger protein-1 (MuRF-1), myostatin, and TNF-α." (PMID 35250869, 2022). "Otherwise, the patients' myostatin levels (r = 0.462, p = 0.003) and HOMA-IR (r = 0.496, p = 0.001) were positively correlated with sarcopenia status." (PMID 35371569, 2022). "We aimed to evaluate sarcopenia and sarcopenic obesity (SO) in patients with type 2 diabetes mellitus (T2DM), possible relationships with serum irisin and myostatin levels, and the effect of glycemic control on SO." (PMID 34190188, 2021). "Fortunately, studies have revealed the potential role of muscle-bone crosstalk involving myokines and osteokines, such as IL-6, irisin, myostatin, RANKL/RANK and osteocalcin, in the development of sarcopenia and osteoporosis in COPD." (PMID 34650518, 2021). "The main strength of the current study was that it simultaneously considered the relationship between several biomarkers, including myostatin, follistatin, oxytocin, BDNF, DHEA, T2 and E2, and osteoporosis and/or sarcopenia in the same study population." (PMID 34641817, 2021). "However, increased serum aromatase activity in liver cirrhosis reduced serum testosterone levels, which was suggested as a potential contributor to sarcopenia, although whether these hormonal changes have an actual influence on protein synthesis and myostatin expression is unknown." (PMID 33807573, 2021). "The negative regulator of muscle mass myostatin (also known as Growth/differentiation factor 8 (GDF-8)) binds primarily to the activin II B receptor (ActRIIB) and is upregulated under catabolic conditions such as sarcopenia and cachexia." (PMID 32911600, 2020).